RN7SKP32 (RN7SK pseudogene 32)
Gene: Miscellaneous RNA gene on chromosome 8 (47,068,021 to 47,068,323, reverse strand). Ensembl gene ENSG00000222099.
Homologues: Orthologues: chimpanzee 7SK (99% identical). Paralogues in human: RN7SKP203 (68% identical), RN7SKP160 (67% identical), RN7SKP184 (66% identical), RN7SKP245 (66% identical), RN7SKP146 (66% identical), RN7SKP86 (66% identical), RN7SKP25 (65% identical), 7SK (65% identical), RN7SKP127 (65% identical), RN7SKP133 (65% identical), RN7SKP180 (65% identical), RN7SKP225 (65% identical), and 284 more.